HGF (hepatocyte growth factor)
Diseases named in the same sentence as HGF in open-access papers (continued):
Sharing a sentence is not in itself a finding about the gene and the disease.
dementia (11 papers, 2011 to 2024). Loss of intellectual abilities interfering with an individual's social and occupational functions. "In addition, higher levels of serum HGF were also associated with pre-dementia and AD." (PMID 34615471, 2021). "Dementia fostered the expansion of microglia and astrocytes with increased expression of HGF (center and right panels)." (PMID 38386085, 2024). "Further supporting this notion, two ongoing phase 2 trials in patients with mild-to-moderate AD dementia (NCT04488419) and Parkinson’s disease (PD) dementia or dementia with Lewy bodies (NCT04831281) are testing a drug targeting HGF and MET." (PMID 39187705, 2024). "Higher plasma levels of CDCP1, OPG, and HGF have been shown to accurately discriminate dementia cases from cognitively normal older adults." (PMID 36737481, 2023). "Dihexa was identified in a screen that assessed the capacity to potentiate the biological activity of HGF and was originally developed as an anti-dementia drug." (PMID 33632328, 2021). "Additionally, to follow up on these biomarker candidates, their ability to discriminate AD from other causes of dementia needs to be examined; indeed, several of these markers have already shown promise for distinguishing AD from frontotemporal lobar degeneration (cystatin C, eotaxin-3, and HGF)." (PMID 21526197, 2011). "Activation of the HGF/MET system induces a variety of proneuronal and procognitive processes, and the neurophysiological effects of HGF are well-suited to promote neuronal survival and potentially address the neurodegenerative cascade observed in AD and other types of dementia." (PMID 36538176, 2023). "In this study, we examined the association of baseline serum HGF with neuroimaging markers of CeVD in a cohort of pre-dementia (cognitive impaired no dementia, CIND) and AD patients." (PMID 29410622, 2018). "However, no study has yet examined the association of serum HGF in patients with prodromal dementia (cognitive impairment no dementia, CIND), AD, or concomitant CeVD." (PMID 29410622, 2018). "While previous studies reported increased HGF levels in the brain and CSF of patients with AD, it is unclear whether peripheral HGF may be related to cognitive impairment and dementia." (PMID 29410622, 2018). "Positive modulation of hepatocyte growth factor (HGF)/MET, a critical neurotrophic signaling system, may promote neuronal health and function, thereby addressing neurodegeneration in dementia." (PMID 36538176, 2023). "Reduced HGF/MET signaling contributes to synaptic pathology in the 5 × FAD mouse model of AD; while FGF2 gene transfer restores hippocampal functions in APP/PS1 mice; CRH (corticotropin-releasing hormone) has been proposed to play important roles in AD and other dementias." (PMID 39234102, 2024). "In addition to demonstrating their relationship to inflammatory diet and incident cognitive impairment/dementia, we identified OPG, HGF, NFATC3, CDCP1, and ITGA11 as differentially expressed at the RNA level in brain tissue of deceased individuals with pathologically defined AD." (PMID 36737481, 2023).
lymphedema (11 papers, 2012 to 2025). Excess fluid collection in tissues, causing swelling. "Currently, an increasing number of case studies support the potential role of HGF mutations in primary and secondary lymphedema." (PMID 40766782, 2025). "HGF is also linked to other genes integral to lymphedema’s molecular–genetic mechanisms, for example, VEGFR-2, which is known for activating angiogenesis." (PMID 38791500, 2024). "Genetic mutations in HGF are also involved in the pathogenesis of lymphedema." (PMID 40766782, 2025). "However, none of these reports provide sufficient details to unambiguously confirm the causative role of HGF mutations in lymphedema development." (PMID 38791500, 2024). "Additionally, genes such as KDR, BMPR2, SERPINE1, IL10, and CCL2, which have been identified as possible candidates for lymphedema through the Associative Network Discovery System, are associated with HGF." (PMID 38791500, 2024). "It has been suggested that patients who develop secondary lymphedema following surgery and/or lymphadenectomy may have a genetic predisposition that places them at-risk for lymphedema, notably mutations in HGF and VEGFR3." (PMID 35743063, 2022). "Mutations in HGF and its receptor cMET have been associated with lymphedema beforehand." (PMID 25383712, 2014). "Interestingly, individuals in this family that harbored mutations in both INPPL1 and HGF showed more severe lymphedema symptoms." (PMID 25383712, 2014). "The role of VEGF-C/VEGFR-3 signaling and HGF/MET signaling in the activation of components of the PI3K/AKT signaling pathway in the pathogenesis of lymphedema should be further explored." (PMID 40766782, 2025). "The HGF/MET signaling pathway plays an important role in the pathogenesis of lymphedema, which is closely related to the interaction of RAS/M APK signaling and PI3K/AKT signaling." (PMID 40766782, 2025). "Regulatory molecules of the HGF/MET signaling pathway are equally able to participate in the progression of lymphedema." (PMID 40766782, 2025). "Another study showed that HGF expression via plasmid transfer ameliorates secondary lymphedema in the rat tail injury model." (PMID 38791500, 2024). "Other strategies in an animal model have demonstrated the efficacy of therapeutic lymphangiogenesis against lymphedema to increase or supplement the growth factors or peptides such as HGF, Adrenomedullin, bFGF, and Angiopoetin-1." (PMID 37175479, 2023). "For example, weekly HGF gene therapy decreased swelling and increased lymphangiogenesis in a rat tail model of lymphedema." (PMID 35145417, 2022). "We are currently preparing to start a clinical trial involving lymphedema patients and expect to observe successful therapeutic lymphangiogenesis management by HGF gene therapy." (PMID 24222916, 2013). "This review highlights the lymphatic biology, the pathophysiology of lymphedema, and the therapeutic lymphangiogenesis using hepatocyte growth factor." (PMID 24222916, 2013). "This study describes a novel mutation in the hepatocyte growth factor (HGF) gene, a previously hypothesized candidate for lymphedema pathogenesis." (PMID 38791500, 2024). "In view of these results, we hypothesized that HGF gene therapy would stimulate the growth of the lymphatic vascular system and alter the course of lymphedema." (PMID 24222916, 2013). "Experimental studies have also shown that HGF may have some utility in treating lymphedema." (PMID 35145417, 2022). "Signaling pathways such as the RAS/MAPK pathway, the PI3K/AKT pathway, the TGF-β1 pathway, and the HGF/MET signaling pathway have been confirmed to play important roles in the development and progression of lymphedema." (PMID 40766782, 2025). "In recent years, new advances and breakthroughs have been made in signaling pathways, including RAS/MAPK, PI3K/AKT, VEGF-C/VEGFR-3, HGF/MET, and TGF-β1, which are important for understanding the pathogenesis and disease progression of lymphedema." (PMID 40766782, 2025).
lymphedema (continued). "Alterations of the VEGFR3 signaling pathway are a common feature of primary lymphedema, and supplementation with VEGFC-releasing patches or administration of HGF or ANG-2 improves the lymphedema condition, at least in animal models." (PMID 36612017, 2022). "Currently, HGF is being developed for clinical application in therapeutic angiogenesis for CLI, and the success of this trial is expected to have fewer barriers to its clinical application against lymphedema." (PMID 37175479, 2023). "Importantly, ADRC implantation has been verified to improve lymphedema in a mouse lymphedema model by enhancing the secretion of several lymphangiogenic factors, such as VEGF-C and HGF, following reparative lymphangiogenesis." (PMID 37175479, 2023).
myocardial ischemia (11 papers, 2013 to 2024). A disorder of cardiac function caused by insufficient blood flow to the muscle tissue of the heart. "A significant angiogenic effect of HGF-producing cells was confirmed in myocardial ischemia models and in a rat model of hind limb ischemia." (PMID 31238604, 2019). "HGF is an angiogenic and antiapoptotic protein that ameliorates cardiac ischemia-reperfusion injury and blockade of endogenous HGF increases infarct size and mortality." (PMID 28408970, 2017). "Furthermore, in a rat model of myocardial ischemia with reperfusion, we found that intra-arterial treatment with HGF/IgG complexes significantly improved vascular integrity and cardiac function." (PMID 35295649, 2022). "It is peculiar that after onset of myocardial ischemia expression of HGF receptor (c-met) increases dramatically indicating local defensive reaction and an attempt to “sensitize” ischemic tissue to effects of HGF." (PMID 29787588, 2018). "HGF-overexpressing ADSCs displayed a better therapeutic efficacy in the improvement of angiogenesis and heart function compared with unmodified ADSCs when applied to a model of myocardial ischemia." (PMID 25501583, 2014). "Our previous study demonstrated adenovirus-HGF was effective in myocardial ischemia models." (PMID 23301013, 2013). "Therefore, we next explored how HGF inhibited fibrosis after myocardial ischemia under diabetic conditions." (PMID 23560074, 2013). "Previously, we reported vaso- and cardioprotective protein complexes formed between HGF and polyclonal, non-specific immunoglobulin (IgG) with therapeutic efficacy in a rat model of myocardial ischemia with reperfusion (MI/R)." (PMID 35295649, 2022).
psoriasis (11 papers, 2009 to 2025). An autoimmune condition characterized by red, well-delineated plaques with silvery scales that are usually on the extensor surfaces and scalp. "Anti-inflammatory effects were additionally linked to MSC-secreted HGF in the treatment of radiation-induced injuries, psoriasis and bronchiolitis obliterans." (PMID 37626914, 2023). "Psoriasis development was associated with an increase in the level of angiopoietin-2 and HGF by 25%, of PDGF by 80%, of TNFα and VEGF twice, and of FGF three times as compared to healthy cells." (PMID 34691360, 2021). "In IMQ-induced psoriasis mouse model, hepatocyte growth factor (HGF) overexpressed-DPSCs were reported to ameliorate erythema, scaling and thickening of psoriatic skin lesions, as well as reduce splenic mass in mice." (PMID 40748586, 2025). "HGF overexpression enhanced the treatment effect of DPSCs on psoriasis by reducing inflammatory responses." (PMID 38077342, 2023). "As a consequence, HGF over-expression enhanced treatment effect of DPSCs on psoriasis mainly by reducing inflammatory responses." (PMID 38202116, 2023). "It was found that there is a significant increase in IL-17A and HGF in HS comparatively similar to psoriasis." (PMID 36532043, 2022). "They found that overexpression of HGF could reduce the inflammatory response, enhance the therapeutic effect of DPSCs on psoriasis, and improve the immunoregulatory capacity of DPSCs." (PMID 37175774, 2023). "The significant induction of TNF-α increased IL-6, IL-8, EGF, HGF, TGF-α, epiregulin, and amphiregulin, but the increase in these cytokines and growth factors were not different among normal skin, uninvolved, and involved psoriasis." (PMID 20161853, 2009).
thyroid cancer (11 papers, 2004 to 2025). "Consistent with this possibility, STI571 treatment of thyroid cancer cells and HeLa cells was reported to increase cell migration in response to HGF." (PMID 25946048, 2015). "Interestingly, the scattering and migration abilities of the thyroid cancer cell line TPC1 were greater after treatment with human HGF." (PMID 38605010, 2024). "Also, there have been earlier reports that hepatocyte growth factor (HGF) and its receptor c-Met are overexpressed in thyroid cancer and HGF treatment increases thyroid cancer cell motility through overexpression of EMT markers." (PMID 27880942, 2017). "A panel of four serum biomarkers (IL-8, HGF, MIG, and IL-12) might assist in the discriminating thyroid cancer and benign thyroid diseases." (PMID 32655554, 2020). "Another study evidenced that a panel of four serum biomarkers (IL-8, HGF, MIG, and IL-12) might assist in discriminating thyroid cancer and benign thyroid diseases (AUC 0.81)." (PMID 32655554, 2020).
acute myeloid leukemia (10 papers, 1996 to 2024). Acute myeloid leukemia (AML) is a group of neoplasms arising from precursor cells committed to the myeloid cell-line differentiation. "In this study, we found that HGF was expressed at both the RNA and protein levels in acute myeloid leukaemia (AML) and chronic myeloid leukaemia (CML)." (PMID 8554973, 1996). "Increased levels of HGF have been found in the bone marrow of acute myeloid leukemia (AML) patients." (PMID 28420162, 2017). "Autocrine production of HGF can activate MET by binding to its ligand FGF receptor (FGFR) and eventually lead to myeloblast growth and survival in acute myeloid leukemia." (PMID 38611065, 2024). "In acute myeloid leukemia (AML), cells that express CSF1R support cancer cells by secreting hepatocyte growth factor (HGF) and other cytokines that help cancer cell survival and proliferation." (PMID 32801364, 2020).
Cognitive impairment (10 papers, 2018 to 2025). Abnormal cognition is characterized by deficits in thinking, reasoning, or remembering. "HGF (hepatocyte growth factor) is a neurotrophic factor with effects on angiogenesis and has been associated with small vessel disease in persons with cognitive impairment and AD." (PMID 37584418, 2023). "The increased levels of HGF seen in SVD-associated cognitive impairment and AD cases in our study may thus indicate adaptive plasticity responses to small-vessel mediated neuronal damage or degeneration." (PMID 29410622, 2018). "Hence, in the present study we examined the association of serum HGF levels with MRI markers of CeVD and cognitive impairment/AD in a memory clinic population." (PMID 29410622, 2018). "Previous studies have shown that activation of NMDA receptors can reverse these scopolamine-induced cognitive deficits, and HGF signaling is known to promote NMDA-receptor activation." (PMID 36538176, 2023). "A total of 238 participants (including 90 cognitively normal (CN) and 148 mild cognitive impairment (MCI)) who had measurements of CSF HGF were included from the Alzheimer’s Disease Neuroimaging Initiative (ADNI) database." (PMID 34615471, 2021). "This suggests that HGF plays an important role in mediating hUC‐MSC‐modulated recovery of cognitive deficits in SAMP8 mice." (PMID 32995116, 2020). "In conclusion, the present study suggests that serum HGF has potential clinical utility as a peripheral biomarker of small vessel CeVD in cognitive impairment and AD." (PMID 29410622, 2018). "Moreover, transfer of HGF alleviated cognitive impairment and oxidative stress, and enhanced angiogenesis and synaptophysin levels." (PMID 40564462, 2025). "In this way, potentiation of NMDA receptors by positive modulators of HGF/MET may offset the cognitive impairment induced by cholinergic deficits seen in the scopolamine model; however, this warrants further exploration." (PMID 36538176, 2023). "Among the 52 inflammatory/immune proteins positively correlated with EDII score, six proteins (CXCL10, CCL3, HGF, OPG, CDCP1, NFATC3) were significantly associated with increased odds of incident cognitive impairment after adjusting for demographic characteristics and cardiovascular risk factors." (PMID 36737481, 2023). "While one of the proteins linked to EDII and incident cognitive impairment (CXCL10) has been nominated as a therapeutic target for AD, three candidate proteins (CCL2, CXCL10, and HGF) are therapeutic targets of ongoing clinical trials for non-neurologic disease." (PMID 36737481, 2023). "However, despite the increase of HGF, the decline of HGF receptor c-MET in the hippocampal pyramidal neurons was revealed in AD patients, which may cause reduction of HGF/c-MET signaling and cognitive impairment." (PMID 40564462, 2025). "In the AD mouse model, UC‐derived MSCs could restore cognitive impairment and also support neural network secretion by hepatocyte growth factor (HGF) and resultant induction of the cMet/AKT/ glycogen synthase kinase-3β (GSK-3β) signaling axis in the hippocampus." (PMID 35842587, 2022). "First, whilst our finding of HGF association with CIND suggests that HGF changes may be an early feature of AD, it is not possible to establish a temporal association between HGF changes and the development of cognitive impairment and AD because of the cross-sectional design of the study." (PMID 29410622, 2018). "Results provide insights into how inflammatory nutritional patterns are associated with an immune-related proteome and identify a group of proteins (CXCL10, CCL3, HGF, OPG, CDCP1, NFATC3, ITGA11) related to future cognitive impairment over a 14-year follow-up period." (PMID 36737481, 2023).
depression (10 papers, 2020 to 2025). "In MDD, psychiatric symptoms, such as anxiety and depression, are also significantly associated with cerebrospinal fluid HGF levels." (PMID 38993198, 2024). "Several studies on depression across various groups have also demonstrated a significant relationship between changes in HGF levels and depression, and HGF may be useful in assessing the severity of depression-related symptoms." (PMID 38993198, 2024). "Despite this, it is unknown if ACEs and ROI are associated with the stimulated production of NGF, SCF, SCGF, HGF, and M-CSF and if alterations in these growth factors mediate the effects of ACEs on the depression phenome." (PMID 37509019, 2023). "However, studies have examined HGF in relation to depression, with one study finding significantly lower serum HGF levels in older individuals with major depression compared with controls." (PMID 36756348, 2022). "Hamilton Depression Rating Scale, core, sleep, activity, somatic anxiety, and delusion subscale scores were significantly and positively correlated with CSF HGF level, while sleep subscale score was positively correlated with CSF S100B and VEGF receptor 2 levels in patients with MDD (p < 0.05)." (PMID 32439851, 2020). "The authors also supported the theory of altered HGF/c-MET signaling in depression with the finding that both MET and HGF mRNA expressions were decreased in brain samples of adult depressed individuals." (PMID 34590201, 2023). "HGF and VEGF are neurotrophic factors and decreased expression of HGF has been reported in depression." (PMID 35082787, 2021). "Hence, the present study was carried out to examine: (a) NGF, SCF, SCGF, HGF and M-CSF, in relation to VEGF, PDGF and FGF, and the neurotoxicity immune profile in MDD; and (b) whether NGF or the other growth factors mediate the effects of ACEs and ROI on the depression phenome." (PMID 37509019, 2023).